SOST (sclerostin)
Diseases named in the same sentence as SOST in open-access papers (continued):
Sharing a sentence is not in itself a finding about the gene and the disease.
uric acid stones (1 paper, 2024). "Interestingly, in patients with uric acid stones the average sclerostin level was higher than in calcium oxalate, brushite and apatite." (PMID 38186870, 2024). "We may thus speculate that sclerostin is involved in the context of metabolic stone disease and the interrelationship of BMI, uric acid stones, urinary acidification, and potentially sclerostin levels." (PMID 38186870, 2024).
urinary tract infection (1 paper, 2021). "Urinary disorders (blood urine present, bacterial test positive, and urinary tract infection) and cardiovascular disorders (electrocardiogram T wave abnormal and increased blood pressure diastolic) were unexpected adverse events for sclerostin inhibitors." (PMID 34744750, 2021).
tumor (44 papers, 2013 to 2026). "Thus, the purpose of our study was to evaluate the expression level of sclerostin in tumor tissue derived from BCBM patients and explore its association with clinical outcome and tumor characteristics, including the presence of lytic bone disease." (PMID 28900298, 2017). "Prior work has shown that blocking sclerostin with neutralizing antibodies (Scl-ab) restores osteoblast function and increases bone mass in MM mouse models, but the tumor growth persists unchecked." (PMID 40847323, 2025). "In oncology, targeted agents that inhibit tumor-derived osteolytic cytokines (e.g., IL-6 or PTHrP) and emerging anti-sclerostin antibodies (e.g., romosozumab) further contribute to bone protection." (PMID 41295054, 2025). "Sclerostin expression was detected in both OSCC tumor cell lines in vitro and was also detected at the OSCC–jawbone interface in clinical cases." (PMID 38247829, 2024). "The experiments showed a significant increase in tumor cell proliferation for the SCC-040 tumor cell line at the higher sclerostin concentrations (5 and 10 ng/mL) after all treatment times (24 h, 36 h, 48 h, 60 h and 72 h, all p-values < 0.05)." (PMID 38247829, 2024). "A Boyden chamber assay was performed to evaluate the influence of sclerostin on tumor cell migration and invasion." (PMID 38247829, 2024). "Tumor cell proliferation rate, migration and invasion ability were increased by rh-sclerostin treatment." (PMID 38247829, 2024). "Inhibition of sclerostin reduces migration and invasion of this tumor entity in a time- and dose-dependent manner." (PMID 38247829, 2024). "The tumor cells were treated with 1 and 5 ng/mL rh-sclerostin, equivalent to the migration assay, and tumor cell invasion into the membrane was evaluated by fluorescence microscopy." (PMID 38247829, 2024). "In the present investigation, we demonstrate significant levels of sclerostin expression in tumor cells at the OSCC–jawbone interface in patients with locally advanced, bone-invasive, growing OSCC." (PMID 38247829, 2024). "We show here for the first time that sclerostin can alter the properties of tumor cells toward a more aggressive phenotype and contribute to a tumor-friendly microenvironment at the OSCC–jawbone interface, thereby promoting bone invasion." (PMID 38247829, 2024). "H-score values ranged from 61 to 127 (MV 94, SD 21), indicating significant sclerostin expression in tumor cells at the OSCC–jawbone interface." (PMID 38247829, 2024). "We have recently shown that human OSCC tumor cells upregulate sclerostin expression under TGF-β treatment and that sclerostin expression has significant prognostic implications for patients." (PMID 38247829, 2024). "The data presented here provide a first indication of a possible involvement of sclerostin function in OSCC bone invasion by altering the cellular properties of tumor cells towards a more aggressive phenotype." (PMID 38247829, 2024). "To further verify the impact of SOST on UM, we constructed a stable SOST knockdown expression OCM-1 cells as well as ocular orthotopic tumor models in nude mice." (PMID 35785219, 2022). "By implanting BALB/c nude murine models in situ, the function of SOST on tumor growth was investigated, followed by immunofluorescence double staining of SOST and LRP5/6." (PMID 35785219, 2022). "Meanwhile, higher tumor volume was found in the model + sh-SOST group than the model + sh-NC group, indicating that SOST suppression accelerated tumor growth." (PMID 35785219, 2022). "Thereafter, we established an animal model of ocular orthotopic tumor implantation in BALB/c nude mice to verify the effects of SOST inhibition on UM tumor formation." (PMID 35785219, 2022). "Positive stains of sclerostin were detected in immature bone in tumor-like lesions, such as fibrous dysplasia and osteofibrous dysplasia." (PMID 35160258, 2022).
tumor (continued). "Consistent with our results, the mRNA expression of SOST in RB cells is lower than that in normal retina tissues, and depletion of SOST promotes the proliferation and invasion of RB cells and reduces tumor cells apoptosis." (PMID 35356205, 2022). "Immunohistochemistry demonstrated that SOST expression was lower in tumor cells of the model + sh-SOST group in comparison to that of the model + sh-NC group." (PMID 35785219, 2022). "For translation to clinical applications, SOST-neutralizing antibodies suppressed the bone metastatic microenvironment and prolonged the survival of tumor-bearing mice." (PMID 36581888, 2022). "Silencing the expression of SIRT1 contributed to boosted expression of SOST, thus suppressing the growth of tumor cells." (PMID 35356205, 2022). "Sclerostin was injected intraperitoneally for 7 days to examine the suppression of tumor size and extension of survival." (PMID 34885123, 2021). "Recent studies examining tumor mediated suppression of osteoblast differentiation have shown that tumor cells secrete the WNT antagonist sclerostin." (PMID 34503118, 2021). "Kaplan–Meier curves and survival data demonstrated that sclerostin significantly inhibited tumor growth and improved survival." (PMID 34885123, 2021). "Since sclerostin can serve as a therapeutic target for myeloma bone disease, preclinical study reveals that anti-sclerostin monoclonal antibodies inhibit tumor growth and bone disease in combination with the proteasome inhibitor carfilzomib." (PMID 34503251, 2021). "An additional concern is that the use of an anti-sclerostin antibody results in elevated Wnt signaling, which exacerbates tumor progression." (PMID 31698687, 2019). "Most importantly, tumor-bearing mice deleted for sclerostin exhibited an increase in the number of osteoblasts, which correlated with an increase in bone formation when compared to tumor-bearing mice present for the gene." (PMID 29867053, 2018). "Osteoblast activity in tumor-bearing mice deleted for sclerostin remained at levels comparable to control mice injected with saline indicating rescue of osteoblast function in part by deletion of sclerostin." (PMID 29867053, 2018). "Specifically, tumor-bearing mice deleted for sclerostin exhibited a 60% improvement in the number of osteolytic lesions and a 74% decrease in the area of osteolytic lesions compared to tumor-bearing wild-type mice." (PMID 29867053, 2018). "Then, Scl-Ab treated mice exhibited reduced expression of sclerostin protein in tumor tissue as shown by western blot analyses." (PMID 28900298, 2017). "In xenograft model, sclerostin inhibition improved survival of nude mice and prevented osteolytic lesions resulting from tumor metastasis." (PMID 28900298, 2017). "Tumors were confirmed by H&E staining and tumor sections were stained immunohistochemically to determine the expression of sclerostin." (PMID 28900298, 2017). "In addition, a significant effect was also demonstrated for the highly proliferative PCI-13 tumor cell line for all sclerostin concentrations after treatment periods of 24 h, 36 h and 48 h (all p-values < 0.05)." (PMID 38247829, 2024). "To further explore these interesting findings, we investigated the influence of sclerostin on the proliferation, migration, and invasion of OSCC tumor cells in an in vitro approach and evaluated sclerostin expression at the OSCC–jawbone interface in clinical cases." (PMID 38247829, 2024). "The increase in sclerostin expression during this process may represent a priming of tumor cells prior to local bone invasion." (PMID 38247829, 2024). "Pharmacological sclerostin inhibition prevented bone loss and preserved bone strength in preclinical studies without significantly affecting tumor growth." (PMID 38247829, 2024). "To date, the cellular/molecular mechanisms by which anti-sclerostin releases the suppression of osteoblasts in the tumor microenvironment remain unclear." (PMID 37174109, 2023).
tumor (continued). "Further analysis showed that LRP5 and LRP6 membrane receptors presented lower expressions in tumor cells of the model + sh-SOST group than that of the model + sh-NC group, demonstrating that SOST suppression could decrease the expressions of LRP5 and LRP6." (PMID 35785219, 2022). "We show serum DKK1 and BCMA as possible correlates of tumour burden, and that serum sclerostin may correlate with bone mineral density." (PMID 36612090, 2022). "In situ tumor formation in murine eyes showed that SOST knockdown promoted tumor growth." (PMID 35785219, 2022). "In addition, in tumor-bearing mice with a genetic deletion of sclerostin, there was a 50% increase in trabecular bone volume as well as an increase in the number of osteoblasts compared to tumor-bearing, wild-type mice." (PMID 33572757, 2021). "An increase in tumor volume was suppressed in the sclerostin group, and a significant difference was found at 3 weeks after transplantation (control: 972.68 ± 391.52 mm3, sclerostin: 399.18 ± 163.17 mm3, p = 0.0032)." (PMID 34885123, 2021). "Importantly, sclerostin antibody treatment showed 80% survival of animals with MDA-MB-231 tumor growth in the tibia with significantly higher bone mineral density (BMD), BV/TV, and trabecular thickness." (PMID 34503118, 2021). "The western blot results showed that in EO771 cells, A5 CM downregulated tumor-promoting genes such as Sclerostin, Lrp5, β-catenin, MMP9, Runx2, TGFβ, and Snail and elevated the level of an apoptosis marker, cleaved caspase 3, more substantially than did Y4 CM." (PMID 34230453, 2021). "An increase in tumor volume was suppressed in the sclerostin group, and a significant difference was found at 2 weeks after transplantation (control: 2672.75 ± 838.32 mm3, sclerostin: 806.64 ± 787.82 mm3, p = 0.017)." (PMID 34885123, 2021). "This treatment strategy could also inhibit the osteoclastic RANKL and Sclerostin expression from tumor cells, thus further attenuating downstream osteoclastogenesis." (PMID 33052249, 2020). "In addition, combined anti-sclerostin antibody and proteasome inhibitor treatment improved bone lesions and reduced the number of tumor cells." (PMID 31698687, 2019). "Furthermore, tumor-bearing mice deleted for sclerostin exhibited a 50% increase in trabecular bone volume compared to tumor-bearing wild-type mice." (PMID 29867053, 2018). "Similarly, use of an antibody to sclerostin in tumor-bearing mice resulted in an increase in the number of osteoblasts/bone surface which correlated with increased trabecular bone volume." (PMID 29867053, 2018). "As such, we hypothesized that decreased sclerostin would suppress osteolytic bone lesions and reduce tumor burden, which may represent a target for inhibiting cancer-induced bone diseases and facilitating restoration of normal bone homeostasis." (PMID 28900298, 2017). "Importantly, suppressed sclerostin prevented osteolytic lesions resulting from tumor metastasis in vivo." (PMID 28900298, 2017). "Additionally, a number of factors that inhibit osteoblast differentiation [dickkopf-1 (DKK-1) and sclerostin (SOST)] have been reported to be secreted by tumour cells." (PMID 27761364, 2016). "However, we cannot preclude additional paracrine factors also contributing to tumor formation since transcripts for other secreted growth regulators (SOST, BMP7, BMP8A, WNT5B, WNT10B, and FGF21) exhibited increased abundance in SHP2-depleted pellet cultures." (PMID 24875294, 2014). "In addition, MM cells and cells of the tumor microenvironment secrete Wnt antagonists, such as Dkk1 and sclerostin, which suppress osteoblast function and hinder bone repair, highlighting the need to restore osteoblast function to repair damaged bone in MM patients." (PMID 40847323, 2025). "In addition, sclerostin appears to be involved in the establishment of a tumor-friendly microenvironment by inhibiting osteoblast differentiation and function and promoting osteoclast formation and activity at the site of tumor invasion." (PMID 38247829, 2024).
tumor (continued). "Additionally, Wnt-1, β-catenin, cyclin-D1, MMP2, and MMP9 as well as Ki-67 levels were higher in tumor cells of the model + sh-SOST group than that of the model + sh-NC group, demonstrating that SOST suppression was capable of activating Wnt/β-catenin signaling in ocular orthotopic tumor models." (PMID 35785219, 2022). "First, we demonstrate that neutralizing sclerostin preserves the efficacy of BT-GSI, an anti-tumor therapeutic agent." (PMID 40847323, 2025). "In a pilot study, we have shown that a human OSCC tumor cell line treated with transforming growth factor beta (TGF-β) upregulates SOST gene expression and that sclerostin protein expression has a significant prognostic impact on patients." (PMID 38247829, 2024). "SOST interacted with STAT3 to enhance the TGF-β/KRAS signaling, increasing both tumor growth and bone metastasis." (PMID 36581888, 2022). "Taken together these data show the relevance of the Wnt signalling inhibitors of SOST and DKK-1 for implantology and bone augmentation, as well as for tumor development and cancer therapy." (PMID 31031968, 2019). "Future studies will show how effective targeting of SOST and DKK-1 can be applied to stimulate regeneration and for tumor therapy." (PMID 31031968, 2019). "The immunohistochemical data confirm high sclerostin expression at the OSCC–jawbone interface, which may maintain a tumor-friendly microenvironment and support bone invasion." (PMID 38247829, 2024). "The results presented are the first data suggesting a possible involvement of sclerostin in the bone invasion process of OSCC, which deserves further investigation and may be a potential approach for drug-based tumor therapy." (PMID 38247829, 2024). "The tumor growth curve and weight of mice were measured and the results exhibited that tumor growth and weight in mice infected with oe-P-p38 MAPK + sh-NC were reduced in comparison with that in mice infected with oe-NC + sh-NC or oe-P-p38 MAPK + sh-SOST." (PMID 35356205, 2022). "In the same way, pharmacological inhibition of sclerostin with the antisclerostin antibody in immunocompetent mice reduced osteolysis and resulted in the elevation of bone-formation markers without altering tumor growth." (PMID 35160258, 2022). "Among the tumor tissues from BCBM, 13 (86.7%) exhibited strongly positive expression of sclerostin." (PMID 28900298, 2017). "Three subgroups [serine proteinase inhibitor clade E member 2(SERPINE2) +, CCL23 +, and sclerostin (SOST) +] mainly originate from normal tissue, while subgroups 6 (ACKR1 +) and 1 [potassium voltage—gated channel subfamily E regulatory subunit 3 (KCNE3) +] are enriched in tumor tissue." (PMID 41035074, 2025). "However, in a recent study, administering anti-sclerostin one week before tumor inoculation resulted in no major changes in tumor volume/area." (PMID 37174109, 2023). "Promising agents with bone-anabolic actions that do not directly inhibit tumor proliferation include TGFβ inhibitors and neutralizing antibodies against the WNT inhibitors DKK1 and sclerostin (which are negative regulators of bone formation)." (PMID 25757219, 2014). "In the current study, the negative association could reflect different biologic events possibly due to the fact that sclerostin activity is a part of a physiological process of bone remodeling, and is not secreted by cancer cells as opposed to DKK1 which is produced by tumor cells." (PMID 30227689, 2018).
bone disorder (36 papers, 2013 to 2025). "Deficiency of sclerostin causes van Buchem disease and sclerosteosis, both rare sclerosing bone disorders." (PMID 38186870, 2024). "As a negative regulator of bone homeostasis, the increased level of sclerostin was observed in skeletal disease and bone loss." (PMID 39342093, 2024). "Sclerostin is a secreted glycoprotein that blocks the canonical Wnt/β-Catenin pathway and has gradually emerged as a novel target for treatment of skeletal disease." (PMID 37925419, 2023). "Further longitudinal studies are needed to establish the course of sclerostin during different phases of disease and its exact effects in acromegalic osteopathy." (PMID 34448099, 2022). "The present review summarizes the existing knowledge of sclerostin’s role in the pathogenesis of numerous skeletal diseases and its role as a potential target for treatment." (PMID 35160258, 2022). "In a model of CKD with adynamic osteopathy, increased bone expression and blood level of sclerostin were closely related to dietary phosphorus intake." (PMID 32458213, 2020). "The relationship between plasma sclerostin levels and mineral and bone disorder (CKD-MBD) in HD patients has been studied previously." (PMID 30584645, 2019). "Antibodies against sclerostin and dickkopf-1 are currently being evaluated as potential therapy for treating bone disorders." (PMID 30496210, 2018). "The absence of sclerostin causes sclerosing bone disorders such as sclerosteosis or Van Buchem Disease." (PMID 37108735, 2023). "Sclerostin has been identified as an important regulator of bone homeostasis through inhibition of the canonical Wnt-signaling pathway, and it is involved in the pathogenesis of many different skeletal diseases." (PMID 35160258, 2022). "Although sclerostin was proven to be a crucial therapeutic target for skeletal diseases, its molecular mechanism of regulation and degradation remains unclear." (PMID 34361085, 2021). "Two rare human bone disorders, sclerosteosis and van Buchem disease, are characterized by dramatic increases in bone mineral density (BMD) and have been genetically traced to mutations in the Sost gene locus, which codes for sclerostin." (PMID 34502021, 2021). "Therefore, based on current evidence, we hypothesize that three different phases of osteopathy can be identified, and that sclerostin levels, although there might be large interindividual variability, are likely to differ between these phases." (PMID 34448099, 2022). "Here, we examined the kinetics of sclerostin protein degradation in vitro and in vivo, the mechanism regulating the rapid decline in osteocyte sclerostin protein, its relevance in vivo in bone physiology during ulnar load, and its dysfunction in skeletal disease." (PMID 33779549, 2021). "Hetero-DS (Amgen), also known as AMG 147, is a bispecific antibody constructed on an IgG2 backbone, that targets sclerostin and DKK1 for the treatment of bone disorders, including fracture healing and bone formation." (PMID 40394415, 2025). "Instead, bone loss is mostly from cortical bone in subjects with CKD mineral and bone disorder (CKD-MBD), and their iPTH, alkaline phosphatase, Klotho, sclerostin, and fetuin A levels are pronouncedly altered." (PMID 27398932, 2016). "Despite these limitations regarding biomarkers in uremic cardiovascular disease we see a convincing rationale to introduce sclerostin in CKD-mineral and bone disorder." (PMID 24112318, 2013). "These insights suggest that targeting the sclerostin–Wnt signaling pathway could represent a promising therapeutic approach for managing IJO and other pediatric bone disorders characterized by reduced bone formation." (PMID 39727804, 2024). "Therefore, it is not surprising that the investigations of Wnt inhibitors, especially sclerostin and DKK, become the focus of research regarding the pathophysiology and pharmacotherapy of bone disorders." (PMID 36837860, 2023).